MICAL2 (microtubule associated monooxygenase, calponin and LIM domain containing 2)
Diseases named in the same sentence as MICAL2 in open-access papers (continued):
Sharing a sentence is not in itself a finding about the gene and the disease.
cancer (16 papers, 2016 to 2025). A tumor composed of atypical neoplastic, often pleomorphic cells that invade other tissues. "Previous studies have indicated that, in addition to being highly expressed in cancers, MICAL2 is associated with poor prognosis." (PMID 38326344, 2024). "MICAL2 is highly expressed in several types of aggressive, poorly differentiated human epithelial cancers, as well as in cancer-associated neo-angiogenic capillary endothelia." (PMID 36064550, 2022). "MICAL2 is enriched in the nucleus in human cells and is a microtubule-associated monooxygenase and a novel cancer-promoting factor involved in angiogenesis, cells proliferation, and deformation." (PMID 35461306, 2022). "In vitro, MICAL2 knock-down resulted in mesenchymal to epithelial transition, reduction of viability, and loss of motility and invasion properties of human cancer cells." (PMID 26689989, 2016). "Up to now, MICALs involvement in human cancer was completely unexplored except for a report of MICAL2 splicing variants identified in prostate cancer." (PMID 26689989, 2016). "This suggests that MICAL2 may be a promising therapeutic target against cancer motility; however, the mechanisms underlying the MICAL2-mediated effect on cancer cell migration remain unclear." (PMID 33842533, 2021). "Since cell adhesion and motility play a key role during EMT, and MICAL2 has been implicated in growth cone dynamics, we asked whether MICAL2 expression might affect cancer cell adhesion in vitro." (PMID 26689989, 2016). "In addition, MICAL2 was highly expressed in ECs of the numerous cancer-associated capillaries." (PMID 26689989, 2016). "MICAL2 functions as a new gene that modulates EMT, a mechanism implicated in cancer proliferation and invasion." (PMID 40943497, 2025). "To begin to understand the cellular signaling pathways that signal via MICAL2, we screened the Cancer Cell Line Encyclopedia (CCLE) for genes that correlated with MICAL2 expressions using the nearest neighbors analysis." (PMID 38137053, 2023). "Although much of the focus of therapeutic targeting of Axl in cancer is on receptor inhibitors, these studies point to the potential value of inhibiting MICAL2 or SRF/MRTF-A signaling to block the effects of elevated Axl in cancer." (PMID 38137053, 2023). "Lastly, since MICAL2 is upregulated in diverse cancers, we also wanted to determine if Axl shows increased expression in cancer." (PMID 38137053, 2023). "Although these gene correlations were observed based on an analysis of cancer datasets, it will be important to determine if Axl also regulates MICAL2 and SRF/MRTF-A in development and other physiological processes." (PMID 38137053, 2023). "Molecule interacting with CasL 2 (MICAL2), a cytoskeleton dynamics regulator, are strongly expressed in several human cancer types, especially at the invasive front, in metastasizing cancer cells and in the neo-angiogenic vasculature." (PMID 34946600, 2021). "Up to now, although MICAL2 role in many human diseases is far from being clear, it is known to exert significant biological impacts on multiple cancer types." (PMID 34946600, 2021). "MICAL2-positive cells are found in the invasive front of many cancers, as well as in metastasizing cancer cells inside emboli." (PMID 33842533, 2021). "Subsequently, we investigated the mechanisms by which MICAL2 exerts its proliferative effects in these cancer cells." (PMID 34650666, 2021). "Particularly, high expression of MICAL2 correlates with EMT and thus with cell migration, whereas MET occurs when MICAL2 is turned off, or decreased in cancer cells." (PMID 32811811, 2020). "Conversely, MICAL2 expression was undetectable in cancer cells of well differentiated, intestinal-type tumors." (PMID 26689989, 2016). "To search for novel metastatic factors, we investigated a possible role in cancer for MICAL2, a protein involved in controlling cytoskeleton plasticity, a trait extremely relevant to cell rearrangements and motility in metastatic dissemination." (PMID 26689989, 2016).
cancer (continued). "Given the peculiar localization of MICAL2-positive cells on the cancer invasive front, we wondered how this would correlate with the tumor cells proliferative state." (PMID 26689989, 2016). "Since several primary carcinoma specimens showed MICAL2-positive cells on the cancer invasive edge and in intravasal tumor emboli, we tested the contribution of MICAL2 to invasive properties of cancer cells in vitro." (PMID 26689989, 2016). "So MICAL2 is probably turned on by specific stimuli in the cancer microenvironment and its expression, after having accompanied/sustained cancer cell migration, is turned off at the metastatic site where the intensity of those signals has faded." (PMID 26689989, 2016). "To search for novel genes involved in metastasis, we investigated the possible role of MICAL2 in cancer." (PMID 26689989, 2016). "MICAL2 (molecules interacting with CasL 2) was one of the downregulated genes, and it has been found to exacerbate cells invasion and migration in various cancers." (PMID 35461306, 2022). "Moreover, silencing of MICAL2 promotes mesenchymal to epithelial transition, inhibits the viability as well as the motility and invasive properties of human cancer cells." (PMID 33842533, 2021). "Although MICAL2 is known to mediate the oxidation of actin filaments to regulate F-actin dynamics, relatively few studies have investigated the potential role of MICAL2 during cancer cell migration." (PMID 33842533, 2021). "Interestingly, vimentin and CTNNB1 over-expression and/or cytoplasmic accumulation (as we found in cancer cells expressing high level of MICAL2 in vitro) are both known predictors of hematogenous metastasis in human cancer." (PMID 26689989, 2016). "Our data showing sharp decrease of ROS production in MIC2-KD cells suggest that endogenous over-expression of MICAL2 in human cancer might generate high ROS level with a consequent cell-autonomous, pro-metastatic, pro-angiogenic effect during EMT." (PMID 26689989, 2016). "Directional migration requires cell polarity, but MIC2-KD cells lacked a clearly polarized arrangement in 2D and 3D assays, suggesting that in cancer MICAL2 endogenous over-expression might promote invasion." (PMID 26689989, 2016). "This feature suggested that deregulated expression might be sufficient to derange MICAL2 function, a trait in common to other actin-binding proteins involved in cancer." (PMID 26689989, 2016). "All observations in primary and metastatic human tumors suggested that MICAL2 expression is ‘on’ in a subpopulation of primary cancer cells seemingly detaching from the origin and prone to actively migrate, in individual mode, resist anoikis and travel to distant sites." (PMID 26689989, 2016). "Moreover, recent evidence unveiled the involvement of MICAL2 in cancer cell migration." (PMID 34946600, 2021). "However, despite the known role of MICAL2 in actin oxidation, how MICAL2 influences cancer cell migration remains largely unknown." (PMID 33842533, 2021). "Overall, the co-expression of these genes with MICAL2 most likely reflects the MICAL2-dependent activation of SRF/MRTF-A-dependent gene expression in various cell contexts, including cancer." (PMID 38137053, 2023). "For this, we firsts analyzed the mRNA levels of MICAL2 in The Cancer Genome Atlas Stomach Adenocarcinoma (TCGA-STAD) dataset, and found that MICAL2 expression was significantly higher in tumor tissues than in normal tissues." (PMID 36064550, 2022). "This revealed a set of genes shared with human eTreg cells from affected sites in JIA, RA, and cancer including BATF, VDR, MICAL2, TOX2, KAT2B, PFKFB3, and IL12Rβ2." (PMID 33976194, 2021). "MICAL2 was addressed as a regulator of EMT and the reverse process mesenchymal to epithelial transition (MET) in several cancer types." (PMID 32811811, 2020). "MICAL2 acts as a novel gene that regulates EMT, a process involved in cancer growth and invasion." (PMID 38326344, 2024).
cancer (continued). "Taken together, our observation regarding MICAL2 expression under physiological conditions is not in line with the literature about cancers." (PMID 32811811, 2020). "Endothelial cells (ECs) of neo-angiogenic capillaries that extensively branch into the cancer mass showed a very intense MICAL2 immunostaining, but no expression of MICAL1 and MICAL3, suggesting a different role of MICAL proteins within neo-angiogenic ECs." (PMID 26689989, 2016). "Altogether, data showed MICAL2 expression was high in aggressive primary cancer and in metastatic emboli, but barely or not detectable in cancer cells at metastatic sites." (PMID 26689989, 2016).
tumor (14 papers, 2012 to 2025). "Recent studies showed that molecule interacting with CasL2 (MICAL2) could be a novel tumor growth factor, and it is closely associated with tumor growth and invasion." (PMID 34868922, 2021). "MMP2, a member of the Matrix metalloproteinases family, was positively correlated with MICAL2, confirming that MICAL2 shows potential for promoting tumor metastasis by degrading the ECM." (PMID 38326344, 2024). "In recent years, MICAL2 has been found to be highly expressed in many tumors and promote tumor progression by inducing tumor cell proliferation and migration." (PMID 38326344, 2024). "Previous studies have indicated that Microtubule Associated Monooxygenase, Calponin and LIM Domain Containing 2 (MICAL2) is highly expressed in many tumors and promotes tumor progression." (PMID 38326344, 2024). "Within our sample cohort, the BHLHE40 motif upstream of MICAL2 is accessible in LM and luminal A/B tumor cells and is less accessible in basal-like tumor samples." (PMID 39478117, 2024). "On the contrary, the border of the tumor with surrounding tissues was distinct in the MICAL2-knockdown group." (PMID 34868922, 2021). "Bioluminescence also showed that the tumor size of the NC group was larger than the MICAL2-knockdown group." (PMID 34868922, 2021). "Recent studies have demonstrated that MICAL2 is highly expressed in tumor and accelerates tumor progression and it is deemed to be a novel tumor-promoting factor." (PMID 32647495, 2020). "MICAL2 was a recently identified proto-oncogene, which increased cell proliferation to accelerate tumor growth, and promoted the expression of EMT-related proteins to increase cell metastasis." (PMID 31565549, 2019). "MICAL2-positive cells were localized at the tumor infiltrating front (17/17 samples, 100%) rather than within the neoplastic core (p = 0.0001)." (PMID 26689989, 2016). "In diffuse, signet ring adenocarcinomas, MICAL2 expression was high within the tumor mass and in scattered neoplastic cells infiltrating the gastric wall." (PMID 26689989, 2016). "Overall, QRT-PCR showed MICAL2 up-regulation in poorly differentiated, aggressive tumor of the lung, kidney and stomach compared with paired normal tissues, and in association with metastasis." (PMID 26689989, 2016). "When variable differentiation grades were present within the same tumor, MICAL2 immunolabelling was higher in the less differentiated areas." (PMID 26689989, 2016). "In ccRCC, the subcellular localization of MICAL2 was either cytoplasmic, nuclear, or both with cellular pattern variability within the same tumor." (PMID 26689989, 2016). "Additionally, a separate study identified MICAL2, a tumor promoter, as a nucleoplasmic shuttle protein dependent on MYH9 and its C-terminal fragment." (PMID 39149512, 2024). "Moreover, MICAL2 was recently identified as being a tumor-promoting factor able to accelerate tumor progression." (PMID 36064550, 2022). "Further investigation using scratch and invasion assay are necessary to understand whether MICAL2 is involved in cell migration of non-tumor cells." (PMID 32811811, 2020). "It is also likely that MICAL2 may have an impact in non-tumor cell migration since depolymerization/repolymerization cycles are required for cell rolling." (PMID 32811811, 2020). "Wound healing was conducted to determine whether MICAL2 promotes the migration of tumor cells." (PMID 34868922, 2021). "Furthermore, the results of Western blotting of the tumor showed that PCNA, cyclin D, and vimentin protein were substantially overexpressed in the scramble control group in comparison with the MICAL2-knockdown group." (PMID 34868922, 2021). "Also the inverse correlation with Ki-67 expression level suggested that MICAL2 expression might occur in relatively few (compared with the tumor mass) but critical cells endowed with a motile, invasive phenotype at the tumor edge, rather than proliferating in situ." (PMID 26689989, 2016).
MICAL2 also shares sentences with these, for which no sentence is quoted: colorectal cancer (4 papers); adenocarcinoma (2); bladder cancer (2); anaplastic thyroid carcinoma (1); cardiovascular diseases (1); clear cell renal cell carcinoma (1); Duchenne muscular dystrophy (1); dyslipidemia (1); follicular thyroid carcinoma (1); gastric intestinal type adenocarcinoma (1); gynecologic cancer (1); head and neck cancer (1); Hypertension (1); leprosy (1); LGMD type 2E (1); metabolic disorders (1); metastasis (1); neurodegenerative disease (1); Obesity (1); papillary renal cell carcinoma (1); papillary thyroid carcinoma (1); renal cell adenocarcinoma (1); skin aging (1); squamous cell carcinoma (1); Stomach (1); thyroid (1).